IL6 (interleukin 6)
Diseases named in the same sentence as IL6 in open-access papers (continued):
Sharing a sentence is not in itself a finding about the gene and the disease.
colon carcinoma (continued). "Meanwhile, IL-6 and MMP9 have been shown to promote the growth of colon cancer." (PMID 24397824, 2014). "IL-6 and IL-11 mRNA expression were increased in colonic tumors compared with non-tumor tissue in both Iron/DSS and Control/DSS mice (P<0.05)." (PMID 24223168, 2013). "However, MAT explants obtained from Crohn's disease patients had a significant higher level of expression of inflammatory mediators (IL-6, MCP-1) and leptin and adiponectin when compared to MAT obtained from patients with colon carcinomas (n = 5; # p<0.05)." (PMID 21829567, 2011). "For independent SNP associations, we observed associations with IL6 and IKBKB in colon cancer but not rectal cancer." (PMID 21129206, 2010). "This can be explained by the observation of a constitutive secretion of IL-6 by the MDA-MB-231 cells, which could be responsible for an autocrine loop for IL-6 secretion, as has been proposed for colon cancer." (PMID 20637124, 2010). "Although these substances influence colon carcinoma cell growth, their ability to regulate IL-6 activity in this cell type has not yet been evaluated in detail." (PMID 18205904, 2008). "Another study proposed that mechanisms of quercetin in treating colon cancer may involve inhibition of the TLR4/NF-κB signaling pathway as well as the reduction in the production of inflammation factors, including TNF-α, Cox-2, and IL-6." (PMID 38243957, 2025). "Notably, we observed a similar IL-6 secretion pattern in CAFs exposed to cisplatin, another platinum-based drug, strongly suggesting a broader mechanism of platinum resistance in colon cancer (data not shown)." (PMID 40718440, 2025). "Moreover, after miR-155-5p is transferred to colon cancer cells through M2 MDEs, it targets ZC3H12B and negatively regulates the stability of IL-6 mRNA, increases IL-6 release by tumor cells, and suppresses T-cell immune responses, promoting immune escape in colon cancer." (PMID 40612677, 2025). "Additionally, it has been shown that CAFs from colon cancer promote IL8/CXCR2-mediated monocyte adhesion and attraction through upregulation of VCAM-1 expression and IL-6 production, and subsequently promote polarization to an M2 phenotype by expression of CD163 and CD206." (PMID 38606999, 2024). "In this exploratory analysis of insufficiently physically active colon cancer survivors with low to moderate inflammation at baseline, randomization to 150 min/wk of moderate-intensity aerobic exercise for 24 weeks reduced concentrations of hs-CRP and IL6 in those with stage III disease." (PMID 38148846, 2023). "Herein, using a murine model of intestinal-type colon cancer we report the presence of high levels of SCF and IL-33 in the TME which coincides with the accumulation of TAMCs with a connective-like phenotype that through the production of TNF-α and IL-6 contributes to a pro-inflammatory environment." (PMID 37730723, 2023). "In this regard, recent research has shown that colon cancer cells release a spectrum of factors into the TME, including TNF-α, interleukin-6 (IL-6), interleukin-8 (IL-8), plasminogen activator inhibitor-1 (PAI-1), MMP1, and tumor-derived miRNAs that may contribute to this process." (PMID 37760840, 2023). "Thus, TORC1 activation might be an important molecular mechanism mediating the effects of PGE2 on colon tumor growth, inducing pro‐tumorigenic transcription of genes including NR4A2, COX2, AREG, and IL‐6." (PMID 35920319, 2023). "As expected, PCE at the indicated concentrations could inhibit the cell proliferation of IL-6-induced colon cancer cell lines HCT-116 and HT-29 but did not affect stimulated cancer cells." (PMID 36900505, 2023). "IL-1β has also been demonstrated to re-wire the DNA methylome of colon cancer cells by increasing DNMT3a and ablating DNMT3b expression, with minimal changes to DNMT1, leading to reduced CpG island methylation at the promoter regions of the IL-6 and IL-8 proinflammatory cytokine genes." (PMID 35757000, 2022).
colon carcinoma (continued). "Similarly, co-culture of non-stimulated macrophages with NO-producing colon cancer cells led to an increase in IL-6 levels and significantly decreased IL-10 secretion." (PMID 35660630, 2022). "In colon cancer, TFR1 was overexpressed and high expression of TFR1 could activate the IL-6/IL-11-STAT3 signaling pathway and promote the proliferation and apoptosis of colon epithelial cells, thus aggravating the injury of colon mucosa and leading to the occurrence of colon cancer." (PMID 36082181, 2022). "IL-1β reduced genome methylation of human colon cancer epithelial Caco2 cells and induced CpG demethylation at specific sites in the promoters of the inflammatory cytokine genes IL-6 and IL-8, but not of the IL10 gene promoter, resulting in their increased expression levels." (PMID 31557902, 2019). "Other studies have clarified the presence of cytokine (IL-6 and IL-22)-responsive elements in the promoter regions of REG Iα and Iβ and HIP/PAP in pancreatic or colon cancer cells, although it remained unclear whether STAT3 and/or other transcriptional factors actually bind to these elements." (PMID 31780871, 2019). "However, IL-11, rather than IL-6, plays a more prominent role in promoting colon cancer cell growth." (PMID 30736824, 2019). "Thus, our Oncomine analysis of colon cancer identified downregulation of MUC2 and overexpression of IL-6 in colon cancer but not in normal colon tissue." (PMID 28725043, 2017). "However, the effects of MUC2 expression on IL-6 secretion by colon cancer cells have not been determined." (PMID 25322805, 2014). "We conclude from this that in human colon cancer cells, endogenous PG production, even when stimulated by IL-1β, is too low to affect IL-6 production, and that, conversely, the chemopreventive effect on colon cancer development of COX-2 inhibitors does not involve changes of IL-6 expression." (PMID 18205904, 2008). "In addition, ADAM17 also promotes STAT3 activation by induction of EGFR/IL-6 transduction signaling pathways, which ultimately lead to tumor progression; inhibition of the ADAM17/IL-6/STAT3 signaling axis significantly attenuated the growth of colon cancer cells." (PMID 36466812, 2022). "These and other studies have suggested that IL-6 monoclonal antibodies alone do not show significant anticancer effectiveness in advanced colon cancer, or in other solid tumors; however, it cannot be excluded that they may be effective in the early stage of the disease." (PMID 33923292, 2021). "Thus, in colon cancer patients infected with F. nucleatum, an important increase on TNF-α and IL-10 expression levels have been shown in adenomas, a precursor lesion of colon cancer; while into tumor, IL-6 and IL-8 increased levels were induced by F. nucleatum." (PMID 31662752, 2019). "Subjects with stage I and II colon cancer did not have different concentrations of hs-CRP (P=0.26), IL6 (P=0.74), or sTNFαR2 (P=0.44)." (PMID 38148846, 2023). "This phenomenon was described and explained by Corvinus at al., who showed that some colon cancer derived cell lines (HT-29 was included), contrary to the colon cancer tissues, do not express the active form of STAT3, unless incubated with IL-6." (PMID 32121279, 2020). "In this study we have used comparative gene expression analysis and promoter mapping to demonstrate a direct link between IL-6 and MMP expression in colon cancer, via STAT-1 and novel non-canonical SBEs identified in the MMP-1 and MMP-3 proximal promoters." (PMID 28819304, 2017). "CD14HiHLA-DRHi cells from CD/UC surgical resection specimens may induce differentiation of naïve T cells into Th17 cells with a CD163Lo subset able to produce greater IL-1β and IL-6 after TLR stimulation, compared to macro/microscopically normal areas from colon cancer resections." (PMID 30542349, 2018).
colon carcinoma (continued). "IL-6 can be secreted by a large panel of different immune and non-immune cells, whereby lamina propria CD4+ T cells and, in particular, PU.1-driven Th9 cells, dendritic cells, and tumor cells could be identified as the main producers of this cytokine in colon tumors." (PMID 36428508, 2022).
sarcopenia (487 papers, 2005 to 2026). Progressive decline in muscle mass due to aging which results in decreased functional capacity of muscles. "In fact, in line with the mechanisms illustrated above, some metabolites measured in the saliva like NO and inflammatory cytokines (e.g., IL-6) have been indirectly associated with frailty and/or sarcopenia." (PMID 40805993, 2025). "Pro-inflammatory cytokines such as tumor necrosis factor-α and interleukin-6 can cause chronic low-grade inflammation, which contributes to the development of sarcopenia and the pathogenesis of GAD." (PMID 40373026, 2025). "Deficiency in omega-3s, particularly in aging populations, has been linked to elevated IL-6 levels, a cytokine implicated in sarcopenia." (PMID 40732928, 2025). "For example, in sarcopenia, it was found that the reduction in muscle mass was associated with an increase in the secretion of IL-6, TNF-α, and IL-1β by the intramuscular adipose tissue." (PMID 40001498, 2025). "Age (> 70 years), higher ASA score and sarcopenia are preoperative characteristics that were associated with higher IL‐6 serum levels (all p < 0.05)." (PMID 41380167, 2025). "OS is also linked to sarcopenia, an early stage of FS, marked by increased OS markers, lipid peroxidation, and inflammatory indicators like IL-6 and prostaglandins." (PMID 40732928, 2025). "IL-6 also functions as a myokine involved in regulating muscle homeostasis, and its dysregulation has been closely linked to sarcopenia in aging ndividuals." (PMID 40722201, 2025). "Genetic factors, such as IL-6 gene polymorphisms, influence an individual’s inflammatory response, resulting in differences in muscle adaptability and sarcopenia risk." (PMID 41140691, 2025). "Elevated IL‐6 levels have been associated with increased muscle degradation and reduced muscle strength, thereby exacerbating sarcopenia." (PMID 41380167, 2025). "Loneliness not only affects the mental health of older people but can also induce inflammatory responses, leading to increased interleukin-6 and C-reactive protein levels, which are potential risk factors for sarcopenia." (PMID 41013236, 2025). "Elevated IL-6 levels are associated with decreased handgrip strength, lower muscle mass, and increased fat infiltration, all of which characterize sarcopenia." (PMID 40843723, 2025). "Inflammatory markers such as C-reactive protein (CRP) and interleukin-6 (IL-6) are frequently elevated in individuals with inflammatory sarcopenia and are strongly associated with progressive declines in muscle mass and function." (PMID 40277851, 2025). "Studies on the pathogenic mechanisms of sarcopenia and low muscle density have shown that interleukin-6 (IL-6) and TNF-α play key roles." (PMID 39963665, 2025). "Among the pro-inflammatory biomarkers most consistently associated with sarcopenia are IL-6, TNF-α, and CRP." (PMID 41441428, 2025). "Patients with lipodystrophic features showed greater liver stiffness despite lower fat mass, supporting an IL-6–dominant, sarcopenia-linked pathway of fibrogenesis." (PMID 41470883, 2025). "Inflammatory mediators, particularly interleukin-6 (IL-6), are elevated in frailty and sarcopenia, correlating with muscle catabolism and bone loss." (PMID 40700118, 2025). "Different risk groups separated by sarcopenia and high IL‐6 in serum and the distribution of tumour characteristics and survival." (PMID 41380167, 2025). "In particular, previous studies have reported that tumor necrosis factor-alpha (TNF-α) and interleukin-6 (IL-6) are closely linked to sarcopenia." (PMID 40098209, 2025). "Elevated IL-6 levels have been linked to muscle wasting disorders, such as sarcopenia and cachexia, in which sustained inflammation accelerates muscle atrophy and impairs regenerative processes." (PMID 40944148, 2025). "Individuals with sarcopenia showed higher circulating mtDNA and IL-6/IL-8 levels than controls, with mtDNA independently predicting sarcopenia risk." (PMID 41373468, 2025).
sarcopenia (continued). "After adjusting for age, smoking history, BMI, nutritional score, and disease stage, the results demonstrated that elevated IL-6 levels were positively associated with sarcopenia risk (OR=1.229, 95% CI: 1.082–1.399, P=0.025)." (PMID 40265008, 2025). "Increased IL-6 levels are associated with geriatric syndromes including frailty, sarcopenia, and impaired functional capacity." (PMID 40400914, 2025). "One of the major underlying mechanisms of sarcopenia is chronic inflammation, often driven by pro-inflammatory cytokines such as IL-6 and TNF-α." (PMID 40843723, 2025). "Sins IL-6 have been linked to both fatigue and sarcopenia in PD further investigation of a potential shared biological mechanism is warranted." (PMID 40553423, 2025). "Correlation analysis revealed that IL-6 levels were negatively linked with Blautia, and metabolic pathways like purine, arginine, and histidine metabolism were implicated in sarcopenia development." (PMID 39683426, 2024). "This is the first study of which we are aware that investigates potential causal associations for IL-6 and IL-6R with sarcopenia traits using Mendelian Randomization." (PMID 38750566, 2024). "Increased IL-6 as well as IL-6/IL-10 serum levels were positively associated with degree of sarcopenia and increased with age—overall indicative of a systemic inflammatory status that cannot be compensated by anti-inflammatory IL-10 release." (PMID 39683624, 2024). "Sarcopenia is associated with interleukin-6 (IL-6) and C-reactive protein (CRP), which are markers of inflammation." (PMID 38233827, 2024). "In conclusion, Lachnoclostridium is significantly enriched in the intestines of elderly Uygur patients with sarcopenia; the increase in Lachnoclostridium abundance and the decrease in Streptobacillus abundance are associated with high levels of IL‐6." (PMID 38270306, 2024). "Specifically, IL-6, which is closely linked to inflammaging and sarcopenia, has been identified in multiple studies as being associated with PHN." (PMID 38892810, 2024). "Sarcopenia has been associated with chronic inflammation, as it is accompanied by higher levels of inflammatory markers such as IL-6." (PMID 39101140, 2024). "Although these endothelial biomarkers were upregulated by cytokine stimulation, their association with sarcopenia remained unchanged after adjustment, which included IL‐6 in the models." (PMID 38644163, 2024). "With advancing age, cytokine production increases, resulting in elevated IL-6 levels, which increases the risk of sarcopenia." (PMID 38525752, 2024). "Neoplastic-associated sarcopenia was found to correlate with increased IL-6 and CRP levels in post-surgical colorectal cancer patients." (PMID 39683624, 2024). "Population data have indicated that IL-6 and tumor necrosis factor α levels are significantly increased in older adults with sarcopenia; the higher the levels of IL-6 and C-reactive protein, the greater the risk of muscle loss." (PMID 39390392, 2024). "Single nucleotide polymorphisms (SNPs) were employed as genetic instruments for IL-6 and IL-6R to estimate the causal effect of sarcopenia traits." (PMID 38750566, 2024). "Previous investigations have demonstrated an association between Interleukin-6 (IL-6) and muscular dystrophy as well as sarcopenia in the elderly population." (PMID 38319411, 2024). "Frail elderly individuals exhibit elevated levels of tumor necrosis factor-α (TNF-α) in comparison to healthy young adults, and interleukin-6 (IL-6) is significantly associated with sarcopenia." (PMID 39026669, 2024). "Higher levels of IL-6 and IL-10, both indicators of sarcopenia and muscle strength loss, underlay the ongoing inflammatory process compromising muscle quality in dependent patients." (PMID 38338718, 2024). "With regard to this point, persistent systemic levels of IL-6 in the blood were shown to be associated with accelerated muscle loss and the development of sarcopenia in the elderly." (PMID 39683547, 2024).
sarcopenia (continued). "IL-6, a proinflammatory cytokine secreted by many cells including monocytes and T lymphocytes is also associated with sarcopenia." (PMID 37299588, 2023). "A clinical study demonstrated that reductions in the plasma TNF-α and IL-6 values were positively linked to improvements of diagnostic parameters of sarcopenia in HIV-infected individuals who underwent resistance and aerobic exercise training." (PMID 37589754, 2023). "Blood was drawn, and inflammatory biomarkers associated with Sarcopenia (IL-2, IL-4, IL-5, IL-6, IL-8, IL-10, TNF, adiponectin, leptin, resistin, BDNF, sTNFr-1 and sTNFr-2) was analysed." (PMID 37365209, 2023). "The secondary aim was to elucidate the possible mechanistic pathway between blood inflammatory interleukin-6 marker and sarcopenia risk, after taking into account biological, dietary and lifestyle factors." (PMID 37161054, 2023). "Studies in the elderly have found that an increased level of IL-6 is associated with the occurrence of sarcopenia." (PMID 37577356, 2023). "Increased levels of IL-6 have been associated with muscle loss, muscle strength and sarcopenia risk." (PMID 37161054, 2023). "Low-grade chronic inflammation, produced by slight elevations in circulating pro-inflammatory mediators (such as C-reactive protein (CRP), tumor necrosis factor (TNF), and IL-6), is among the causes of inducing sarcopenia." (PMID 38069224, 2023). "Chronic inflammation related to the aging process, which is defined by elevated levels of interleukin-6 and tumor necrosis factor-α, has been a causal factor of decreased cognitive performance and the presence of sarcopenia in the elderly population." (PMID 36901167, 2023). "In fact, interleukin-6 is associated with sarcopenia, which is regarded as the main cause of physical frailty." (PMID 37436687, 2023). "Chronic inflammation is also reportedly associated with sarcopenia, and observational studies have shown increased levels of pro-inflammatory cytokines, tumour necrosis factor-α and interleukin-6 in the ageing muscle of individuals with sarcopenia." (PMID 37928789, 2023). "Our multivariate model, demonstrate that PhA, in association with creatinine, a common renal function, and nutritional marker, and IL-6, a chronic inflammation marker, have, all together, a robust association to sarcopenia in ND-CKD patients." (PMID 35463026, 2022). "Serum interleukin 6 (IL-6), which is increased in cancer-caused sarcopenia, is found in high levels in PTC patients and showed a significant positive correlation with larger tumor size and ETE18." (PMID 35273343, 2022). "Sarcopenia was associated with increased levels of inflammatory cytokine interleukin-6, while beta-blockers were found to decrease the levels of serum interleukin-6." (PMID 36419131, 2022). "25HC inhibits the expression of IL-6, a known contributor to muscle atrophy in sarcopenia, attenuating the loss of muscle mass associated with aging in mice and human cultures." (PMID 35954203, 2022). "Positive associations were present between the severity of sarcopenia and IL-6, IL-17A, and TNF-α levels, while there was an inverse correlation between the presence of sarcopenia and IL-10 level." (PMID 35237317, 2022). "In the Poisson Multivariate Model, the variables that remained significantly associated with sarcopenia were PhA (p < 0.001), IL-6 (p = 0.020), and serum creatinine (p = 0.024)." (PMID 35463026, 2022). "Although the mechanisms underlying cytokines and disability remain to be determined, it is plausible that cytokines (e.g., IL-6, IL-1 and tumor necrosis factor-α) directly cause sarcopenia and functional impairments." (PMID 35492728, 2022). "A key mechanism underlying the impaired immunity in individuals with sarcopenia refers to the abnormal myokines, such as interleukin (IL)‐15, IL‐17, and IL‐6." (PMID 34541518, 2022).